AR (androgen receptor)
Diseases named in the same sentence as AR in open-access papers (continued):
Sharing a sentence is not in itself a finding about the gene and the disease.
breast carcinoma (continued). "In this study, we were interested in utilizing a single cell–based high throughput microscopy platform to characterize modulators of AR levels and localization by comparing the effects of small molecules on endogenous AR across six prostate and breast cancer cell lines." (PMID 26918604, 2016). "Our results suggest that the expression of Lin28A may be an attractive target for therapeutic intervention by enhancing AR in ER-/Her2+ breast cancer." (PMID 27494865, 2016). "Together, these lines of evidence suggest that intracrine androgen synthesis, higher androgen concentrations, and AR expression are strongly associated with a better prognosis, favorable therapeutic outcome, and a reduction in tumor in patients with AR-positive breast cancers." (PMID 27918430, 2016). "NR2C1 suppresses androgen-mediated AR transactivation, which may be of therapeutic interest in AR+/mammary-tumors." (PMID 26894976, 2016). "AR expression has been reported in approximately 80 % of primary breast cancers." (PMID 26459317, 2015). "Indeed, the promoters of several breast cancer genes on the X chromosome, such as AR, HMGB3 and LAGE3, were hypomethylated and the mRNAs were over-expressed in MCF7 and HCC1954." (PMID 25706888, 2015). "AR expression and phosphorylation has been observed in a number of breast cancers." (PMID 25592291, 2015). "The interplay between AR and ER expression in breast cancer is under investigation." (PMID 25871911, 2015). "Therefore understanding the regulatory mechanisms of the functioning of the AR in ER-/AR+ breast cancer will provide many novel targets for the purpose of therapeutic intervention." (PMID 25781993, 2015). "However, the AR has recently received much attention as a novel therapeutic target in breast cancer and a role for AR activation in a proportion of HER2+ cancers has been reported." (PMID 25592291, 2015). "However, increased expression of AR in bladder cancer and ERα-positive breast cancer can be a good prognostic indicator." (PMID 26397136, 2015). "However, stimulation with dehydroepiandrosterone sulfate (DHEAS) induces breast cancer cell proliferation through the ER, but inhibits proliferation through AR." (PMID 26456774, 2015). "A significant number of poorly differentiated breast carcinomas are ER-negative but AR-positive suggesting AR as a useful marker for the further refinement of breast cancer subtype classification and as an independent prognostic factor and therapeutic target for the triple-negative breast cancers." (PMID 25693204, 2015). "Furthermore, the previous study reported that 20% of the hereditary BRCA-related breast cancers had triple-negative phenotype and expressed AR." (PMID 25695063, 2015). "Interestingly, the AR has recently received much attention as a novel therapeutic target in breast cancer." (PMID 25592291, 2015). "Interestingly, TCF4 has only one first-order neighbor identified as breast cancer-related, the androgen receptor AR." (PMID 26043920, 2015). "The recent understanding is that EBR, a member of the BRs, induces apoptosis more effectively in nuclear hormone receptor (NHR)-expressing cancer cell lines, such as LNCaP prostate [with androgen receptor (AR)] or MCF-7 breast cancer cell lines [with estrogen receptor (ER)]." (PMID 26353013, 2015). "Previous work from our laboratory has demonstrated an inverse relationship between the expression of ACSL4 and AR/ER in breast cancer cell lines and tissue samples; the data further suggested that co-expression of both a receptor and ACSL4 was indicative of hormone-independent growth." (PMID 26636648, 2015). "This feature was also characteristic of the prototypical AR in MDA-MB-453 breast cancer cells." (PMID 26554309, 2015). "Confirmation of breast origin may therefore be obtained using immunostaining with mammaglobin, GCDFP-15, and androgen receptor in difficult cases, which seem to fit into the triple-negative category of breast carcinoma." (PMID 25849448, 2015).
breast carcinoma (continued). "Whether the establishment of a feed-forward loop in mammary tumors also follows the initial AR activation remains to be investigated." (PMID 25592291, 2015). "Recent in vitro studies pinpointed the significant influence of estrogen receptor α (ER) status on androgen-dependant cell growth stimulation: androgens tend to inhibit the growth of AR-positive and ER-positive breast cancer cells but stimulate the growth of AR-positive and ER-negative cells." (PMID 24505496, 2014). "However, the clinical significance of other endocrine-related pathways such as androgen and AR signaling has been recently proposed in primary breast cancer patients." (PMID 24552459, 2014). "Triple negative breast cancer in vitro and in vivo models were developed and non-aromatizable androgens were evaluated to test the hypothesis that increasing AR function would reduce breast cancer growth." (PMID 25072326, 2014). "In addition, Farmer and colleagues have previously identified a distinct gene expression pattern in ER-, AR + breast cancers termed molecular apocrine representing 8 to 14% of all breast cancers." (PMID 25103565, 2014). "Moreover, our results demonstrate that HMGCS2 added to the steroid hormone receptor signature (ER-/PR-/AR+) identifies apocrine tumors from other breast cancer subtypes with greater sensitivity as compared to steroid receptor profile alone." (PMID 25389781, 2014). "Further in vitro cellular studies of AR and autophagy in breast cancer are required." (PMID 25140630, 2014). "Indeed, a phase II clinical trial testing bicalutamide as treatment for ER–/AR + breast cancers (NCT00468715) showed some efficacy." (PMID 24451109, 2014). "Yet AR-negative breast cancers respond poorly to hormone therapy with reduced overall survival, while conversely AR-positive cancers are smaller with fewer lymph node metastases corresponding to a better prognosis, thus demonstrating the role of the AR as a biomarker." (PMID 25928046, 2014). "In ER-positive luminal breast cancers, AR has a growth inhibitor role but AR signaling may promote growth of a subset of ER-negative AR-positive breast cancers." (PMID 24505496, 2014). "Furthermore in breast cancer, a recent study has linked the activation of HER2 with the expression of AR." (PMID 24779793, 2014). "In breast cancers, androgen receptor (AR) is more widely expressed than estrogen receptor alpha (ER) or progesterone receptor (PR), and AR has recently emerged as a useful marker for the further refinement of breast cancer subtype classification." (PMID 24451109, 2014). "Despite evidence of benefit, therapeutic efforts with androgens for breast cancer preceded knowledge regarding AR expression and the use of these agents fell from favor due to virilizing side effects, fears of aromatization to estrogen, and the advent of tamoxifen." (PMID 25072326, 2014). "We next tried to confirm the inverse correlation of L1CAM and AR in in breast cancer cell lines." (PMID 25510351, 2014). "This difference in how enzalutamide and bicalutamide affect ER activity may provide insight into the role of AR in breast cancer." (PMID 24451109, 2014). "However, originally as a negative control in experiments where we were antagonizing DHT with enzalutamide, we combined enzalutamide with E2 in ER+/AR + breast cancer cells." (PMID 24451109, 2014). "In addition, the high levels of AR expression in the IACs makes this receptor a promising anticancer therapeutic target for this type of breast cancer, but the ability to exploit AR for therapy remains to be challenging." (PMID 25389781, 2014). "Lysates from four luminal ER + breast cancer cell lines were probed for AR and ER." (PMID 24451109, 2014).
breast carcinoma (continued). "This is consistent with a recent meta-analysis that also suggested a better overall survival for patients with breast tumours with higher androgen receptor (AR) expression, independent of Estrogen Receptor (ER), and new clinical trials targeting AR in breast cancer have already been put in place." (PMID 25608477, 2014). "Breast cancer exhibited lower AR expression than benign breast tissue." (PMID 24922532, 2014). "The AR is expressed in 70 to 90% of breast cancers, comparable with ER?" (PMID 25928046, 2014). "Given the known tumor repressive role of ER beta in breast cancer cell lines, we wondered whether AR also functions as an anti-proliferative effector in ER-positive breast cancer by affecting ER beta expression." (PMID 24552459, 2014). "Importantly, AR expression is detected in about 10 to 50% of triple-negative (ER, progesterone receptor and Her-2) breast cancers that respond poorly to traditional therapies." (PMID 25928046, 2014). "Despite the growing evidence highlighting the potential prognostic and/or predictive role of AR in breast cancer, the mechanisms by which androgen signaling may affect tumor progression still remain not well clarified." (PMID 24552459, 2014). "Indeed, studies in breast cancer using human samples confirm that those tumors that are HER2 positive express higher amounts of the AR." (PMID 24779793, 2014). "This could be related to the relatively small series of analyzed samples (i.e. n = 153) and to the low prevalence of AR positive cases in this specific breast cancer subtype." (PMID 24505496, 2014). "AR overexpression increases tamoxifen resistance in breast cancer models in vitro and in vivo." (PMID 24451109, 2014). "Androgen receptor (AR) is commonly expressed in breast cancers." (PMID 24550933, 2014). "AR expression was higher in those breast cancers which also expressed ER and PR." (PMID 25051360, 2014). "AR may be functionally important in certain breast cancer subtypes, and clinical testing of anti-androgen therapy in patients with such subtypes is ongoing." (PMID 25349530, 2014). "Emerging preclinical and clinical data suggest that AR may serve as a therapeutic target in certain difficult-to-treat breast cancer subtypes, such as TNBC." (PMID 24505496, 2014). "Androgens may inhibit pituitary and ovarian function; however, androgens could also have direct effects because rodent mammary epithelium as well as carcinogen-induced mammary tumors are AR-positive." (PMID 25928046, 2014). "Because tumor cell expression of ERα correlates with tumor size, histologic grade, and axillary node metastasis, it may be difficult to argue that the relatively good prognosis of ERα+ breast cancers should be attributed, in part, to coexpressed AR." (PMID 24324894, 2013). "Thus, the expression of AR is considered to be a good prognostic marker for ERα-positive breast cancer; however, there were some problems in previous studies." (PMID 24403250, 2013). "Interestingly the AR, ER and MR have been shown to inhibit apoptosis in skeletal cells, breast cancer cells, neuronal cells and/or cardiomyocytes, when activated by their receptor-selective agonists, an effect that is most likely cell-specific." (PMID 23658782, 2013). "If the clinical relevance of especially ERβ1 and AR can be firmly established, several new intrinsic subtypes of endocrine-sensitive breast cancers may emerge and subsequently undergo gene expression profiling." (PMID 24324894, 2013). "In addition, the cut-off values for evaluating the positivity of AR expression in breast cancer have varied widely among studies: 1%, low, AR < 10%; intermediate 10 ≤ AR < 50%; high, AR ≥ 50%, 10%;, 75%." (PMID 24403250, 2013). "Second, results of in vitro studies are discordant even in AR+ breast cancer cell lines." (PMID 24324894, 2013).
breast carcinoma (continued). "A phase II trial (NCT00468715) is currently investigating the effectiveness of bicaluamide in ER negative, AR positive breast cancer and a recent study found that AR expression is associated with a favorable prognosis subgroup of chemoresistant TNBC tumors." (PMID 24260093, 2013). "What may be more intriguing about AR as a breast cancer target relates to a novel finding in ER−/AR+/HER2+ tumor samples." (PMID 24324894, 2013). "Interestingly, 10%–35% of triple negative and up to 60% of ER−/PR−/HER2+ breast cancers have been reported to express AR." (PMID 24324894, 2013). "AR expression and breast cancer OS was dependent on ER expression." (PMID 24324816, 2013). "The role of AR in breast cancer is currently unclear and seems to depend on the cellular milieu." (PMID 23593223, 2013). "The expression of AR in patients with ER positive breast cancer could also predict OS benefit, and the HR was 0.39 (95% CI 0.19–0.82); but the same was not predictable in ER negative and TNBC subgroups." (PMID 24324816, 2013). "This suggests that AIs are better for AR-positive postmenopausal breast cancer patients." (PMID 24403250, 2013). "Hence, a functional feedback loop has been postulated in this type of breast cancer which includes AR, HER2, ERK, and an ERK transcription factor that binds to a promoter region on the AR gene." (PMID 24324894, 2013). "Therefore, AR expression was considered to have a profound effect on the prognosis of older (51 years or older) females with ER-positive breast cancer." (PMID 24403250, 2013). "Indeed, although sometimes reported to belong to several molecular subtypes of breast cancer, morphological apocrine carcinomas are almost always ER(-) tumors and, among 19 cases, all were ER(-), PR(-) and strongly AR(+) by IHC." (PMID 23663520, 2013). "In breast cancer, the role of regulatory defects in the AR gene are yet to be fully elucidated." (PMID 22471922, 2012). "Here we demonstrate for the first time that hypermethylation of sections of the AR 5' regulatory region is associated with loss of AR expression in breast cancer cell lines, although not in a small set primary tumours." (PMID 22471922, 2012). "Previous studies in prostate and breast cancers demonstrated that EGF induced AR/ER/Src association, resulting in activation of Src signaling and that Src signals phosphorylated tyrosine residue of AR, provoking its transactivation and cell proliferation." (PMID 22922989, 2012). "Importantly, AR signaling is a potential therapeutic target in ER-/AR+ breast cancer and is currently under investigation in a clinical trial (ClinicalTrials.gov Identifier: NCT00468715)." (PMID 22817771, 2012). "However, for those clinicians who deal with these patients, it is important to bear in mind all of the complex relationships between AR expression in breast cancer and other steroid receptors and growth factors." (PMID 23273269, 2012). "In AR negative breast tumours, mutation screening identified the same mutation (T105A) in the 5'UTR of two AR negative breast cancer patients but not reported in the normal human population." (PMID 22471922, 2012). "A similar result was seen in the MDA-MB-231 breast cancer cell lines that overexpress AR." (PMID 22321971, 2012). "It would be even more difficult to hypothesize on the role of androgen excess and the AR expression in the evolution of breast cancer in female to male transsexual patients due to the small number of such cases reported in literature." (PMID 23273269, 2012). "For the first time we show that DNA hypermethylation in the AR promoter is associated with loss of AR expression in breast cancer cells, although this is not the case in our cohort of tumours from patients with Stage III breast cancer." (PMID 22471922, 2012).
breast carcinoma (continued). "Genetic variants in hormone receptor genes may be crucial predisposing factors for breast cancer, and microsatellites in the estrogen receptor (ESR1, ESR2) and androgen receptor (AR) genes have been suggested to play a role." (PMID 22792352, 2012). "An investigation into the mechanisms responsible for the loss of AR expression revealed that hypermethylation of the AR promoter is associated with loss of AR expression in breast cancer cells but not in primary breast tumours." (PMID 22471922, 2012). "Although there have been no studies targeting this particular subtype with an AR inhibitor, a phase II trial (NCT00468715) is currently ongoing evaluating bicalutamide, a commonly used androgen receptor antagonist, in patients with ER/PR-negative breast cancer." (PMID 22295242, 2012). "In addition, many breast cancers co-express other steroid hormone receptors that can affect AR signaling, further obfuscating the effects of androgens on breast cancer cells." (PMID 22321971, 2012). "Many previous studies have identified AR expression in human breast cancers." (PMID 22321971, 2012). "Moreover, 10% to 20% of ERα/PR-negative breast cancers are AR-positive, which potentially opens the possibility of hormone therapies for these breast cancers as well." (PMID 22321971, 2012). "Similar to ERα, the results confirm that in the high percentage of breast cancers that express AR, gene amplification does not seem to be a major underlying genetic change." (PMID 22321971, 2012). "Interestingly, it has been reported that a subgroup of bladder cancer have high AR expression, suggesting a gene expression scenario similar to AR-positive apocrine breast cancer." (PMID 22839103, 2012). "Androgen receptor overexpression may enhance TAM's agonistic properties in breast cancer and contribute to resistance." (PMID 22033271, 2011). "The androgen receptor (AR) is frequently expressed in breast cancers." (PMID 22033271, 2011). "Since there is growing evidence to support the role of AR as a target for therapy in molecular apocrine breast cancer, the new AR inhibitors may potentially provide additional treatment options in the management of this disease." (PMID 21457548, 2011). "Importantly, a growing body of evidence suggests that AR is a therapeutic target in molecular apocrine breast cancer." (PMID 21457548, 2011). "For pathological classification, this subtype can easily be characterized as ER-/AR+ breast cancer." (PMID 21457548, 2011). "However, the expression of DAX-1 is positively correlated with the expression of AR in breast cancer." (PMID 22035181, 2011). "A combination therapy approach provides an attractive option in the management of ER-/AR+ breast cancer, since it exploits the synergy between AR and MEK inhibitors and at the same time minimizes their potential toxicities by requiring a lower dose of each agent in the combination setting." (PMID 21457548, 2011). "In addition, an ongoing clinical trial has demonstrated that AR inhibition can stabilize disease progression in metastatic ER-/AR+ breast cancer." (PMID 21457548, 2011). "If this finding is confirmed, AR genotyping may provide useful information for selection of endocrine treatment of breast cancer patients." (PMID 22033271, 2011). "Although many breast cancers express AR, the association of AR and AIB1 in breast cancer has not been studied well." (PMID 22035181, 2011). "This might indicate a better effect on breast cancer-free survival for AI in this AR diplotype group, but needs to be confirmed in a larger, independent cohort with longer follow-up." (PMID 22033271, 2011). "Stratification by age of onset, FH, stage, grade ER and AR status failed to reveal any association with breast cancer risk." (PMID 20831839, 2010). "The role of androgens and androgen receptors in breast carcinogenesis is poorly understood, although wide spread expression of AR in breast cancer suggests that it may have significant biological and clinical relevance." (PMID 20831839, 2010).